MIR1306 (microRNA 1306)
Synonyms: hsa-mir-1306; MIRN1306; mir-1306
Gene: MicroRNA gene on chromosome 22 (20,086,058 to 20,086,142, forward strand). Ensembl gene ENSG00000284464.
Gene Ontology:
Biological process: miRNA-mediated post-transcriptional gene silencing
Cellular component: RISC complex
Homologues: Orthologues: chimpanzee ptr-mir-1306 (100% identical), macaque MIR1306 (95% identical), rabbit MIR1306 (91% identical), dog MIR1306 (89% identical), guinea pig MIR1306 (89% identical), mouse Mir1306 (89% identical), pig ssc-mir-1306 (89% identical), zebrafish mir1306 (76% identical).